IGLV1-47 (immunoglobulin lambda variable 1-47)
Description:
V region of the variable domain of immunoglobulin light chains that participates in the antigen recognition. Immunoglobulins, also known as antibodies, are membrane-bound or secreted glycoproteins produced by B lymphocytes. In the recognition phase of humoral immunity, the membrane-bound immunoglobulins serve as receptors which, upon binding of a specific antigen, trigger the clonal expansion and differentiation of B lymphocytes into immunoglobulins-secreting plasma cells. Secreted immunoglobulins mediate the effector phase of humoral immunity, which results in the elimination of bound antigens. The antigen binding site is formed by the variable domain of one heavy chain, together with that of its associated light chain. Thus, each immunoglobulin has two antigen binding sites with remarkable affinity for a particular antigen. The variable domains are assembled by a process called V-(D)-J rearrangement and can then be subjected to somatic hypermutations which, after exposure to antigen and selection, allow affinity maturation for a particular antigen.
Synonyms: IGLV147; V1-17
Tractability: Antibody: its Gene Ontology location is reachable by antibodies, with high confidence; UniProt places it where antibodies can reach, with medium confidence; UniProt predicts a signal peptide or a membrane-spanning region.
Gene: Immunoglobulin variable (V) gene on chromosome 22 (22,357,739 to 22,358,260, forward strand). Ensembl gene ENSG00000211648.
Subcellular location: Secreted; Cell membrane
Pathways (Reactome):
Immune System: Antigen activates B Cell Receptor (BCR) leading to generation of second messengers; CD22 mediated BCR regulation; Classical antibody-mediated complement activation; FCERI mediated Ca+2 mobilization; FCERI mediated MAPK activation; FCERI mediated NF-kB activation; FCGR activation; Fc epsilon receptor (FCERI) signaling; Immunoregulatory interactions between a Lymphoid and a non-Lymphoid cell; Initial triggering of complement; Regulation of Complement cascade; Regulation of actin dynamics for phagocytic cup formation; Role of LAT2/NTAL/LAB on calcium mobilization; Role of phospholipids in phagocytosis
Disease: FCGR3A-mediated IL10 synthesis; FCGR3A-mediated phagocytosis; Potential therapeutics for SARS
Hemostasis: Cell surface interactions at the vascular wall
Vesicle-mediated transport: Scavenging of heme from plasma
Gene Ontology:
Molecular function: antigen binding
Biological process: immune response
Cellular component: blood microparticle; extracellular region; immunoglobulin complex; plasma membrane
Homologues: Paralogues in human: IGLV1-44 (96% identical), IGLV1-36 (83% identical), IGLV1-40 (81% identical), IGLV1-51 (79% identical), IGLV1-50 (75% identical), IGLV2-18 (69% identical), IGLV2-8 (67% identical), IGLV6-57 (67% identical), IGLV2-11 (65% identical), IGLV2-14 (64% identical), IGLV2-23 (64% identical), IGLV2-33 (60% identical), and 81 more.